ERBB2 (erb-b2 receptor tyrosine kinase 2)
Diseases named in the same sentence as ERBB2 in open-access papers (continued):
Sharing a sentence is not in itself a finding about the gene and the disease.
Pca (1 paper, 2014). "While the studies in cell lines and animal models point to a key role of ErbB2 in the pathogenesis of Pca, studies in humans are less clear." (PMID 25215939, 2014). "The finding that ErbB2 expression in the normal rat prostate is inversely related to circulating androgen levels is consistent with studies in cultured Pca cells and Pca tumour xenograft models." (PMID 25215939, 2014). "However, a meta-analysis of the literature between 1996 and 2009 found an increased relative risk for death due to Pca or biochemical (prostate-specific antigen, PSA) recurrence of the disease in patients with moderate to high levels of tumour ErbB2 expression." (PMID 25215939, 2014). "The present study was designed to determine whether or not tumour ErbB2-IR per se is a clinically useful marker of Pca disease outcome, rather than to shed light upon the involvement of the gene product in the pathogenesis of the disease." (PMID 25215939, 2014).
peripheral nerve injury (1 paper, 2013). Injury to a peripheral nerve. "The present study also showed that TLN enhanced NRG receptor signal intensity through increasing Nrg1 mRNA expression and phosphorylation of ErbB2 at a protein level after peripheral nerve injury in STZ-R." (PMID 24288572, 2013).
polyp (1 paper, 2022). A usually exophytic mass attached to the underlying tissue by a broad base or a thin stalk. "ERBB2-mutated SPs displayed increased risks of polyp recurrence, with a median polyp-free interval of 26 months compared to 32 months in wild-type SPs (P < 0.001; HR = 3.7; 95% CI = 2.3–6.0)." (PMID 35402217, 2022). "The findings illustrated that only ERBB2 mutations (n = 5) displayed a significant correlation with polyp recurrence, displaying a shorter median polyp-free interval of 15 months compared to 26 months than the wild types (n = 85) (P < 0.001; HR = 4.9; 95% CI = 1.9–12.8)." (PMID 35402217, 2022). "Furthermore, a multicenter cohort composed by 321 SPs verified that ERBB2-mutated SPs had increased risks of polyp recurrence (P < 0.001; HR = 3.7; 95% CI = 2.3–6.0) and advanced neoplastic lesion (ANL) recurrence (P < 0.001; HR = 10.0; 95% CI = 2.7–36.9) compared with wild-type SPs, respectively." (PMID 35402217, 2022). "ERBB2 mutants displayed increased risks of polyp recurrence in Shanghai Renji center (P < 0.001), while no mutational factor was associated with polyp recurrence in patients from Chongqing TCM or Sichuan centers possibly due to the small sample size." (PMID 35402217, 2022).
rectal NETs (1 paper, 2023). "ERBB2 mutations were frequently identified in well‐differentiated rectal NETs." (PMID 37387515, 2023).
sarcoidosis (1 paper, 2020). Sarcoidosis is a multisystemic disorder of unknown cause characterized by the formation of immune granulomas in involved organs. "Specifically, early T effector cells (ETE) from sarcoidosis patients had significant downregulation of TCR signaling (labeled “SLE T cell signaling pathway” here) and ICOS-ICOSL signaling, as well as PI3K/AKT, ERK/MAPK, NFAT, ERBB2 (TOB), sirtuin, and mTOR signaling, relative to controls." (PMID 33363531, 2020).
schwannomatosis (1 paper, 2024). The least frequent form of the rare genetic disorder neurofibromatosis. "One schwannomatosis patient had three tumors all harboring the same V777L (p.Val777Leu) ERBB2 mutation as reported in our cases." (PMID 39196362, 2024).
solitary fibrous tumor (1 paper, 2024). Solitary fibrous tumor (SFT) represents a diverse group of ubiquitous rare spindle cell neoplasms that may be benign or malignant and that most frequently arises from the pleura and peritoneum and rarely from other sites such as head and neck, liver and skeletal muscle. "Overexpression of IGF2 related to LOI and receptor tyrosine kinase genes including DDR1, ERBB2, and FGFR1 have implicated the IGF2-INSR pathway in sphere formation of solitary fibrous tumor (SFT)." (PMID 38812777, 2024).
steatosis (1 paper, 2021). Increased lipid within the cytoplasm of cells. "The few cases with moderate or strong ErbB2 expression additionally showed a moderate or severe steatosis." (PMID 32591879, 2021). "However, in steatohepatitis, there was even a significant inverse correlation between degree of steatosis and mean score of ErbB2." (PMID 32591879, 2021).
Ta (1 paper, 2024). "Our analysis identified two subgroups in Ta tumors: one with FGFR3 alterations linked to LG tumors and favorable outcomes, and another with alterations in ERBB2, PIK3CA, and ERBB3 mutations, and FGFR1, CCND1, and MYC amplifications, associated mostly with HG tumors and poorer prognosis." (PMID 39410541, 2024).
teratoma (1 paper, 2021). A non-seminomatous germ cell tumor characterized by the presence of various tissues which correspond to the different germinal layers (endoderm, mesoderm, and ectoderm). "Occasionally, ErbB2-iPSC clones when injected non-orthotopically also gave rise to teratomas (data not shown)." (PMID 34044885, 2021).
urethral adenocarcinoma (1 paper, 2026). "In 2023, subsequent resections confirmed HER2-positive, ERBB2-amplified urethral adenocarcinoma." (PMID 42256662, 2026).
vascular malformation (1 paper, 2025). A non-neoplastic disorder that is the result of defects of vascular morphogenesis. "Since ERBB2 is involved in signaling pathways that regulate cell growth and differentiation, it could theoretically play a role in the pathophysiology of vascular malformations." (PMID 40564170, 2025).
ventricular septal defect (1 paper, 2009). The presence of a defect (opening) in the septum that separates the two ventricles of the heart. "Mice with a ventricular-restricted deletion of Erbb2 show ventricular septal defect (VSD) suggesting that the human ortholog ERBB2 could be a potential candidate gene for VSD." (PMID 19245720, 2009).
tumor (16,550 papers, 1989 to 2026). "Regressive mutations in KRAS and SMAD4, as well as specific ERBB2 point mutations, have been shown to influence tumor growth kinetics, metastatic behavior, and responsiveness to targeted or cytotoxic agents." (PMID 41492104, 2026). "In this work, we elucidate the impact of loss of MHC-I expression upon ERBB2 signaling on tumor immune cell evasion and tumor metastasis in SCLC." (PMID 41361170, 2025). "Excessive MUC4 expression is strongly associated with poor differentiation, advanced tumor stage, and high ErbB2 expression." (PMID 40655139, 2025). "Individualized management strategies should incorporate HER2 heterogeneity, hormone receptor co-expression, ERBB2 mutations, and features of the tumor microenvironment." (PMID 41228310, 2025). "With an abundance of 8.6%, the ERBB2 mutation represented a significant driver of the tumor’s behavior, highlighting the potential efficacy of T-DXd." (PMID 41573731, 2025). "Alternations of ERBB2, including overexpression and mutation, have been observed in multiple tumor types." (PMID 40828885, 2025). "Conversely, HER2 overexpression is the hallmark of ERBB2-overexpressing tumours, which also lack ER and progesterone receptor (PR) expression." (PMID 40824193, 2025). "NCCN and ESMO recommend, at minimum, testing for fusions in FGFR2 and NTRK, mutations in IDH1 and BRAF, over-expression or amplifications of HER2/ERBB2, tumor-mutational burden (TMB), and microsatellite instability (MSI)." (PMID 39996880, 2025). "ERBB2 co-amplification was observed in 13.1% to 24.5% of tumors harboring ERBB2 activating mutations, suggesting that mutations can serve as the primary genomic mechanism of ERBB2 activation in multiple tumor types." (PMID 40178042, 2025). "Sequential mutational analysis highlighted the importance of identifying and treating patients harboring ERBB2 oncogenic variants originating from the primary tumor." (PMID 40770324, 2025). "The HER2DX genomic test provides three key scores (relapse risk, pCR likelihood, and ERBB2 mRNA scores) by integrating data from 27 genes with clinical factors, tumor size, and nodal status." (PMID 40900789, 2025). "ERBB2 mutations lead to the constitutive activation of the HER2 pathway, driving tumor proliferation and survival." (PMID 40432921, 2025). "ERBB2 (the gene encoding HER2) amplification or overexpression drives tumor proliferation and metastasis through constitutive activation of downstream MAPK/PI3K signaling pathways." (PMID 40969261, 2025). "Recent advances highlight the complex interplay between tumor-promoting and tumor-suppressing immune signals—such as IL-4Rα-driven progression and IL-24-mediated inhibition—as well as novel targets like ERBB2 and tumor-associated autoantigens." (PMID 40508013, 2025). "Changes in HER2 expression in tumor cells are mainly caused by mutations, amplifications or overexpression of the HER2 gene (erbB2)." (PMID 41188605, 2025). "Transcriptionally, all 16 cell lines express various levels of other tumor-associated antigens, such as mesothelin, survivin, folate receptor and Erbb2." (PMID 40642792, 2025). "The receptor tyrosine-kinase ERBB2 is among the most intensively studied tumor-associated antigens for targeted therapies and thus serves as a highly relevant model system for retargeting lentiviral vectors." (PMID 41472234, 2025). "Whereas ERBB2 KD mutations predominated pan-tumor, the ERBB2 mutational profile varied significantly between cancer types." (PMID 40178042, 2025).
tumor (continued). "Given that resistance to HER2-targeted agents is heterogeneous and not fully understood, we conducted an exploratory analysis of previously reported response-modifying co-alterations with either ERBB2 amplification or mutation(s) across select tumor types." (PMID 40178042, 2025). "Activated ERBB2/ERBB3 mutations have been reported to promote tumor cell proliferation and migration, as well as increase PD-L1 expression to induce immune evasion, and are associated with worse patient survival." (PMID 40116917, 2025). "In conclusion, in our cohort of patients with various ERBB2-mutated tumor types who had exhausted standard treatment options, HER2-targeted treatment resulted in clinically meaningful efficacy in a substantial number of patients." (PMID 40770324, 2025). "Both glucose uptake and the expression of the glucose transporter Glut1 (Slc2a1), but not that of Glut2 (Slc2a2), Glut3 (Slc2a3), or Glut4 (Slc2a4), were elevated in Cpt1a-deficient ErbB2 tumor cells." (PMID 39097623, 2024). "The next-generation sequencing has shown PIK3CA E545K, SMAD4 1309-1G, and ALK E717K gene mutations, receptor tyrosine kinase 2 (ErbB-2) amplification, microsatellite stability, and low tumor mutational burden of 6.3 mutations per megabase." (PMID 38215117, 2024). "Combining the ketogenic diet, composed of LCFAs, or an anti-ErbB2 monoclonal antibody (mAb) with Cpt1a deficiency significantly perturbs tumor growth, enhances apoptosis, and reduces lung metastasis." (PMID 39097623, 2024). "From an institutional cohort of 2638 ECs subjected to clinical tumor-normal panel sequencing, 69 (2.6%) with pathogenic ERBB2 mutation(s) were identified, of which 11 were also ERBB2-amplified." (PMID 39031567, 2024). "In this study, we identified host genetic variants that predispose Erbb2-driven tumour development and metastasis using the CC mouse resource." (PMID 39067134, 2024). "For patient 32, the identified tumor lineages showed convergent evolution of ERBB2 activation through distinct known activating mutations and the focal high amplification of ERBB2." (PMID 38503755, 2024). "This resistance is thought to arise from a range of mechanisms, including the activation of alternative signaling pathways, ERBB2 gene mutations, and tumour heterogeneity." (PMID 39067134, 2024). "The gastric lesion demonstrated a wild-type ERBB2, high tumor mutation burden (TMB-H, 35.67 mutation/Mb), MSI-H, and PD-L1 negativity (tumor cell proportion score = 0%, combined positive score < 1)." (PMID 39612421, 2024). "In the three cases of the initial tumor with an ERBB2 mutation, the mutations were present with a high allelic frequency." (PMID 38287892, 2024). "The histogenesis of this tumor, its appropriate classification and the potential benefit of targeting the underlying ERBB2/ ERBB3 tyrosine kinase mutation remain to be verified in the future." (PMID 39196362, 2024). "We developed multiplex digital PCR assays to detect and quantify ERBB2 mutations in circulating tumor DNA from liquid biopsies." (PMID 38287892, 2024). "Tumor cell proliferation was primarily attributed to activation of the ERBB2 and CDK12 pathways; lung and lymph node specific mutations were also detected." (PMID 38539567, 2024). "Collectively, these data argue that loss of Cpt1a disrupts redox homeostasis in ErbB2+ tumor cells, triggering an oxidative stress response through upregulation of Nrf2 and its target genes." (PMID 39097623, 2024). "This is associated with poor prognostic factors, including ERBB2 overexpression, larger tumor size, and a higher histological grade." (PMID 39769140, 2024). "Each WEE1 variant was found in a single tumor while the ERBB2 variants were each found in two different tumors for a minimum putatively damaging gene mutation frequency of 6% and 24% respectively." (PMID 38778091, 2024). "In NMIBC, ERBB2 alterations were associated with a higher tumor stage and grade and linked to worse PFS." (PMID 39410541, 2024).
tumor (continued). "Individuals with the BsmI allele exhibit significantly elevated levels of erbB-2 expression, indicating the involvement of other tumor-related molecules in the functional effects of the BsmI polymorphism." (PMID 39201651, 2024). "Alterations in HER2 expression in tumor cells primarily arise from the mutation, amplification or overexpression of the HER2 gene (erbB2)." (PMID 38308374, 2024). "Mutations on the ERBB2 gene in tumor samples cause lower survival probability with a 1.43 hazard ratio (p = 0.08)." (PMID 38254834, 2024). "They reported that ERBB2 amplification was highly detected in patients with high tumor mutation burden, and CDK12 rearrangement in patients with ERBB2 amplification." (PMID 38473240, 2024). "One patient with an EGFR exon 21 (L858R) mutation had 30% residual viable tumor cells in the resected tumor, and another patient with an ERBB2 mutation had 70% residual viable tumor cells post-induction therapy." (PMID 39349061, 2024). "Loss of EGFR or ERBB2 in human Panc‐1 cells results in delayed migration, reduced proliferation rate, and increased tumor growth behavior." (PMID 37341059, 2023). "Across 396 analyzed patients, prevalence of potentially actionable alterations was comparable with the expected prevalence in advanced disease (13% FGFR2/3, 20% PIK3CA, 13% ERBB2, and 37% with elevated tumor mutational burden ≥10 mutations/megabase)." (PMID 37601688, 2023). "In contrast, RAD21 low mRNA showed significant association with low tumor grade in ERBB2-high cohort." (PMID 37474724, 2023). "ERBB2 overexpression was more likely to be found in high-grade tumors and was associated with tumor progression." (PMID 37173881, 2023). "In particular, in the more sensitive test procedure for GC, the correlation analyses showed associations between ERBB2 overexpression, tumor progression, high tumor grade, and the occurrence of an ERBB2 amplification or gain." (PMID 37173881, 2023). "Univariate analysis data indicate that in ERBB2-high cohort mRNA expression of RAD21 low was significantly associated with tumor grade (p = 0.011)." (PMID 37474724, 2023). "Many epithelial tumors contain mutations of ERBB2, and clinical studies indicate that they are correlated with tumor progression." (PMID 37033651, 2023). "Similar to previous studies in both groups, the gene mutation rate significantly increased as the tumor became larger, except for ERBB2, which was more mutated in smaller lesions." (PMID 36611170, 2023). "EphA2 also amplifies the oncogenic signalling of the RTK erbB2 (HER2), and the loss of EphA2 in the mammary epithelium of mice slowed down tumour development and metastasis." (PMID 36830852, 2023). "On the other hand, low expression of RAD50/BARD1 in ERBB2-low cohort had a significant association with higher tumor stages (p = 0.013)." (PMID 37474724, 2023). "For each of the three tumor types, the data suggest a positive association between HER2 protein expression level and ERBB2 amplification ratio." (PMID 37119523, 2023). "In HBC, the evaluation of cell differentiation proteins is frequently performed in association with routine diagnostic markers (ER, PR, ERBB2, and Ki-67) to better classify this tumor." (PMID 36899736, 2023). "Abnormal ERBB2 expression is associated with poor prognosis and tumor recurrence in patients with HCC." (PMID 37174100, 2023). "CNV inference further revealed that the tumor cells contained the chromosome 17q gain signature, which is associated with amplification of the ERBB2 oncogene." (PMID 37508518, 2023). "Next-generation sequencing using primary tumor tissue and plasma revealed an ERBB2 mutation (c.2454_2455insG), which explained the favorable clinical outcome of the patient." (PMID 38067272, 2023). "Correlation and survival analyses show that ERBB2 overexpression and amplification were linked with high-grade and high-stage tumors and with tumor progression." (PMID 37173881, 2023).